INS (insulin)
Diseases named in the same sentence as INS in open-access papers (continued):
Sharing a sentence is not in itself a finding about the gene and the disease.
vitamin D deficiency (284 papers, 2008 to 2026). A nutritional condition produced by a deficiency of VITAMIN D in the diet, insufficient production of vitamin D in the skin, inadequate absorption of vitamin D from the diet, or abnormal conversion of vitamin D to its bioactive metabolites. "These variables appear to either exacerbate vitamin D deficiency or magnify its impact on glucose metabolism and insulin regulation during pregnancy." (PMID 40806014, 2025). "We used the baseline clinical data to determine the prevalence of vitamin D deficiency and its association between vitamin D status and cognitive function, adiposity, and insulin sensitivity." (PMID 40284166, 2025). "Vitamin D deficiency reduces insulin sensitivity, increases triglyceride and low-density lipoprotein cholesterol production, and reduces high-density lipoprotein cholesterol synthesis." (PMID 40362671, 2025). "Vitamin D deficiency has emerged as a candidate factor due to its recognized role in insulin secretion and insulin signaling pathways." (PMID 41406483, 2025). "Vitamin D deficiency can indirectly impact calcium levels during insulin secretion, affecting signal transduction and glucose transporter activity." (PMID 39935579, 2025). "In a cross-sectional study of 64 obese children, vitamin D deficiency was prevalent in the subjects with lower insulin sensitivity and higher inflammatory markers." (PMID 40431370, 2025). "Conversely, vitamin D deficiency has been demonstrated to increase parathyroid hormone concentration, inhibit insulin secretion by islet B cells, and induce insulin resistance by regulating intracellular free calcium concentration." (PMID 40704311, 2025). "Animal models show that vitamin D deficiency impairs insulin secretion, which is reversible upon supplementation." (PMID 40943440, 2025). "The highest postprandial insulin values were observed in individuals with severe vitamin D deficiency (<25 nmol/L), showing a median of 94.9 μU/mL and a wide interquartile range of 11.7–370.5 μU/mL." (PMID 40868057, 2025). "Experimental studies have shown that vitamin D deficiency or receptor dysfunction reduces insulin secretion, while supplementation enhances calcium-mediated release." (PMID 41149081, 2025). "In animal models, vitamin D deficiency has been linked to reduced insulin levels, while supplementation has been shown to restore islet insulin secretion." (PMID 39796548, 2024). "Vitamin D deficiency appears to be linked to the induction and progression of DM, with a clear relationship between vitamin D, insulin secretion, insulin tolerance, and pancreatic beta-cell dysfunction." (PMID 38592202, 2024). "Regardless, insulin is a powerful anti-catabolic hormone, and alterations to insulin secretion or sensitivity can potentially promote muscle atrophy in individuals born preterm, given their predisposition to vitamin D deficiency and low muscle mass." (PMID 38785544, 2024). "A study in 2004 demonstrated that the concentration of 25(OH)D is positively correlated with insulin sensitivity and negatively correlated with β-cell function in cases of vitamin D deficiency." (PMID 39193371, 2024). "Postmenopausal women are at an increased risk of developing vitamin D deficiency, which is linked to diet, lifestyle, changes in body composition, insulin sensitivity, and reduced physical activity." (PMID 38935105, 2024). "Vitamin D deficiency in childhood is related to increased levels of circulating inflammatory mediators, IR, and decreased insulin sensitivity." (PMID 39275320, 2024). "Today, for newly diagnosed patients, dietary indications and insulin therapy based on personalized nutrition should help correct their documented nutritional defects, vitamin D deficiency, and high ω-6:ω-3 PUFA ratios." (PMID 39519472, 2024). "Several in vivo and ex vivo studies in rats have indicated that vitamin D deficiency in vivo resulted in reduced serum insulin levels and impaired islet insulin secretion in isolated islets." (PMID 37111216, 2023).
vitamin D deficiency (continued). "Vitamin D deficiency can affect insulin secretion and sensitivity and play an essential role in the onset of MetS." (PMID 37895163, 2023). "Increasing evidence points to a strong association between vitamin D insufficiency and a decrease in insulin secretion in both people and animal models." (PMID 36742396, 2023). "Vitamin D deficiency has been associated with T2D and Vitamin D supplementation improves insulin sensitivity in insulin resistant individuals." (PMID 37941908, 2023). "In prior reports, vitamin D deficiency has been shown to interfere with insulin synthesis and secretion." (PMID 37188155, 2023). "Several studies have observed an association between vitamin D deficiency and the impairment of the glucose-mediated secretion of insulin in rat pancreatic β-cells." (PMID 36835159, 2023). "Subgroup analysis results for the two primary outcomes of blood glucose and insulin shown that the low-dose, short-term and Vitamin D deficiency subgroups were statistically significant compared with other subgroups (all P < 0.05)." (PMID 37524765, 2023). "It was also confirmed that vitamin D deficiency is linked to the reduction of the excretion of insulin from the pancreatic β-cells." (PMID 36833019, 2023). "Vitamin D deficiency has been shown to reduce insulin secretion, whereas vitamin D repletion has exhibited improved insulin secretion in animals." (PMID 37892510, 2023). "In terms of glycaemic control, seven studies examined the association of vitamin D deficiency with glycaemic control and two studies shown an inverse association between vitamin D deficiency and insulin levels." (PMID 37242192, 2023). "Vitamin D deficiency is involved in abnormal glucose metabolism, altered insulin secretion and T2DM." (PMID 37072813, 2023). "From a biological perspective, vitamin D deficiency/insufficiency as a determinant of diabetes risk is plausible, given that both impaired insulin secretion and action have been reported with vitamin D insufficiency." (PMID 35631254, 2022). "Vitamin D deficiency lowers intracellular calcium levels, which inhibits insulin release by cells, further worsening glucose tolerance." (PMID 36043008, 2022). "Individuals with vitamin D deficiency exhibited a 48 percent reduction in insulin secretion compared to individuals with optimal levels of vitamin D. Thus, indicating that vitamin D stimulates the pancreas to produce insulin." (PMID 35340511, 2022). "Multiple studies have shown that in the presence of abdominal adiposity, vitamin D deficiency is linked to inflammation and decreased insulin sensitivity, whereas vitamin D treatment improves both outcomes." (PMID 36043008, 2022). "Higher insulin requirements in vitamin D deficiency and insufficient groups were found in different studies." (PMID 34766458, 2022). "Our study marked that the group with Vitamin D deficiency had higher levels of glucose, insulin, and HOMA-IR compared to the group with sufficient Vitamin D level (p<0.001)." (PMID 36199866, 2022). "Insulin secretion depends on calcium level, and it has been noted that vitamin D deficiency prevents glucose-facilitated insulin secretion." (PMID 35345711, 2022). "Rabbits and mice with experimentally induced vitamin D deficiency show low insulin secretion, and following vitamin D supplementation, a normalization of insulin secretion is observed." (PMID 36676692, 2022). "Previous studies have demonstrated that knocking out vitamin D receptors to cause vitamin D deficiency resulted in impaired insulin secretion induced by glucose." (PMID 36362806, 2022). "A high prevalence of vitamin D deficiency and even an inverse association with insulin sensitivity markers have been shown for PCOS patients." (PMID 35566720, 2022). "The same result was shown in SIR—Studies in animals that vitamin D deficiency is correlated to impaired insulin sensitivity, and that vitamin D supplementation increased insulin secretion." (PMID 35223754, 2021).
vitamin D deficiency (continued). "In vitro studies have shown that beta cells from human pancreatic islets of subjects with vitamin D deficiency are insulin resistant, thus directly linking the two phenomena." (PMID 33652581, 2021). "The vitamin D receptor is expressed by β cells in the pancreas and in musculoskeletal and adipose tissues, among other peripheral tissues, and vitamin D deficiency can compromise the capacity of β cells to convert pro-insulin into insulin." (PMID 33802330, 2021). "In subjects with vitamin D deficiency, vitamin D supplementation leads to improved insulin secretion and glucose tolerance." (PMID 34070202, 2021). "Patients with vitamin D deficiency were more insulin resistant and showed increased oxidative stress (those with severe deficiency) but no elevated systemic inflammation as compared to individuals with vitamin D values over 20 ng/mL." (PMID 34445049, 2021). "Vitamin D deficiency can affect insulin secretion and resistance; thus, it plays a role in the occurrence and development of T2DM." (PMID 32149047, 2020). "Combined hyperandrogenism and vitamin D deficiency led to decreased autophagy in the liver and altered insulin signaling in the ovaries." (PMID 31509973, 2019). "Parathyroid hormone (PTH) levels rise with vitamin D deficiency and increased parathyroid hormone levels have been evidenced to reduced insulin sensitivity." (PMID 31259115, 2019). "Vitamin D modulates the immune system, and several studies have demonstrated that, in the presence of central adiposity, vitamin D deficiency correlates with inflammation and reduced insulin sensitivity, while vitamin D supplementation improves them." (PMID 31266190, 2019). "Studies have shown that vitamin D deficiency cause insulin insensitivity and insulin sensitivity improved with vitamin D supplementation." (PMID 31259115, 2019). "The review presents literature data indicative of a close pathogenic relationship between vitamin D insufficiency and impaired tissue insulin sensitivity." (PMID 30881343, 2019). "Several studies have demonstrated that vitamin D deficiency contributes to impairment of glucose-mediated secretion of insulin in rat pancreatic β-cells." (PMID 30959886, 2019). "Vitamin D deficiency is very common among seniors and has been linked to both low muscle mass and high fat mass as well as metabolic disturbances such as insulin resistance." (PMID 30477276, 2018). "Accumulating evidence from various studies has linked vitamin D status to insulin secretion and insulin resistance; however, the relationship between vitamin D deficiency and glycemic control remains conflicting." (PMID 29808168, 2018). "In vivo, vitamin D deficiency causes dysregulation of glucose metabolism by increasing insulin resistance through deteriorating β-cell function and mass." (PMID 29631547, 2018). "For example, changes in parathyroid hormone (PTH) levels, a hormone involved in bone remodeling, and Vitamin D deficiency, an important nutrient in bone metabolism, affect the synthesis and release of insulin." (PMID 29710852, 2018). "Studies have shown that glucose induced insulin secretion is impaired by knocking out vitamin D receptor and by inducing vitamin D deficiency." (PMID 29320437, 2018). "Vitamin D replenishment restores insulin secretion and sensitivity in patients with type 2 diabetes and established vitamin D deficiency." (PMID 29449829, 2018). "This study aimed to assess the impact of vitamin D deficiency, alone or in combination with a high fat diet, on markers of metabolic function including visceral adiposity, hepatic lipid accumulation, and insulin sensitivity." (PMID 28880231, 2017). "During times of vitamin D deficiency, beta cell function is blunted and insulin secretion is diminished." (PMID 28575036, 2017). "Vitamin D insufficiency has been associated with increased fat infiltration in skeletal muscle and contributes to decrease in insulin sensitivity." (PMID 27883024, 2016).
vitamin D deficiency (continued). "Several studies reported an impaired insulin release in association with vitamin D deficiency, and vitamin D supplementation has been shown to improve insulin release in randomized controlled trials." (PMID 26833056, 2016). "Our novel finding is that circulating betatrophin was increased in subjects with vitamin D deficiency and the associations with blood pressures, lipids, glucose/insulin traits, creatinine and uric acid were largely dependent on vitamin D status." (PMID 27716289, 2016). "On the other hand, an association of vitamin D deficiency with impaired insulin secretion has been observed in different studies." (PMID 27221615, 2016). "Vitamin D deficiency has been reported to be associated with an increase in parathyroid hormone, which in turn is associated with decreased insulin sensitivity." (PMID 26488726, 2015). "Studies have revealed the association between vitamin D deficiency and changes in blood glucose and insulin levels as well as sensitivity of the target tissues to insulin." (PMID 25340161, 2014). "It has been well established that vitamin D deficiency is correlated with high body fat and glucose levels and decreased insulin sensitivity." (PMID 24397367, 2014). "Maternal vitamin D-deficiency in the third trimester in an Indian population was linked to higher fasting insulin resistance and smaller arm muscle area at the age of 9.5 years in the offspring." (PMID 23457566, 2013). "Several studies have shown that some complications in ESRD patients, including anaemia, lipid and insulin abnormalities, cardiovascular risks and early mortality, would be improved after correction of vitamin D deficiency." (PMID 23800151, 2013). "Since the early 1980’s, it has been demonstrated that pancreatic insulin secretion is inhibited by vitamin D deficiency, suggesting a role for this vitamin in the regulation of endocrine pancreatic function, especially in the β cell." (PMID 23855914, 2013). "After adjusted for age, sex, BMI, PAL, smoking and alcohol consumption, subjects with vitamin D deficiency indicated significant differences in metabolic variables compared with vitamin D sufficiency group except for insulin, TC, LDL-C and apoB." (PMID 23320821, 2013). "The vitamin D deficiency group had significantly greater waist circumference, BMI, fasting plasma glucose, insulin, HOMA-IR, triglycerides, and diastolic blood pressure and lower HDL cholesterol compared to vitamin sufficiency and insufficiency groups." (PMID 22958612, 2012). "In rats, vitamin D deficiency induced impairment of insulin secretion and glucose tolerance that was partially corrected after vitamin D replenishment." (PMID 22347618, 2012). "Deterioration of insulin action in peripheral tissues also has been reported in vitamin D deficiency." (PMID 22363895, 2012). "Alvarez and Ashraf found in their meta-analysis of both cross-sectional and prospective studies that vitamin D insufficiency (20–29 ng/ml) and deficiency (less than 20 ng/ml) have direct and indirect effects on insulin secretion and insulin action." (PMID 21747838, 2011). "Gedik and Akalin first reported impairment in insulin secretion in 4 relatively healthy subjects presenting with vitamin D deficiency, and their insulin secretion was normalized after 6 months of vitamin D supplementation." (PMID 20011094, 2010). "Vitamin D deficiency may also affect insulin sensitivity and indirectly promote DR development by interacting with DR‐related biological processes." (PMID 40264687, 2025). "Vitamin D deficiency may also contribute to DKA susceptibility by impairing insulin secretion and sensitivity." (PMID 41149081, 2025). "Therefore, although correcting vitamin D deficiency is important for overall health, its role as a therapeutic agent for improving insulin sensitivity in pediatric obesity requires further investigation through well-designed, large-scale clinical trials." (PMID 40431370, 2025).
vitamin D deficiency (continued). "Consequently, vitamin D deficiency can destabilize intracellular and extracellular calcium, which in turn affects normal insulin secretion." (PMID 39935579, 2025). "In conclusion, while vitamin D deficiency is commonly observed in obese children and has been associated with impaired insulin sensitivity and increased inflammatory markers, the evidence regarding the effectiveness of vitamin D supplementation in improving metabolic outcomes remains inconsistent." (PMID 40431370, 2025). "Second, vitamin D deficiency may impair pancreatic β-cell functions, thereby compromising the secretion of insulin." (PMID 38594739, 2024). "On one hand, vitamin D deficiency may contribute to dysregulated lipid metabolism through its effects on insulin sensitivity, pancreatic β cell function, and inflammatory pathways." (PMID 39498411, 2024). "The authors also found that serum vitamin D concentration positively correlates with insulin sensitivity, which is unsurprising given that vitamin D deficiency can cause poor insulin sensitivity (via decreases in insulin receptor expression) and impaired β-cell function." (PMID 38785544, 2024). "Conversely, vitamin D deficiency may reduce calcium ion concentration in islet cells, impairing related signaling pathways and affecting insulin synthesis and secretion, leading to elevated blood glucose levels and potentially resulting in GDM." (PMID 39749014, 2024). "Hypophosphatemia in sepsis may result from: poor nutrition, steroid therapy, vitamin D deficiency, inappropriate fluid therapy, refeeding syndrome, diuretics, insulin, catecholamines." (PMID 37568451, 2023). "Possible mechanisms by which vitamin D deficiency may contribute to cardiovascular disease include increased renin–angiotensin levels, impaired insulin sensitivity, and increased inflammation." (PMID 37959300, 2023). "Additionally, in vitro, and in vivo studies show that vitamin D receptor knockout or vitamin D deficiency impairs glucose-induced insulin secretion, and the insulin secretory response improves after vitamin D supplementation in both animals and humans." (PMID 37107924, 2023). "Vitamin D deficiency may alter insulin secretion and sensitivity, which play a crucial role in the development of MetS." (PMID 37242192, 2023). "Vitamin D has essential immunoregulatory properties, and vitamin D deficiency may play a role in the development of T2DM by affecting insulin secretion." (PMID 37836571, 2023). "Furthermore, vitamin D deficiency adversely affects insulin synthesis and secretion, increasing the risk of developing T2D." (PMID 38068813, 2023). "Moreover, vitamin D reduces the activity of the NF-kB signaling pathway, thus vitamin D deficiency decreases peripheral insulin sensitivity as a result of an increased systemic inflammation." (PMID 37964189, 2023). "Studies have shown that vitamin D deficiency negatively impacts insulin sensitivity." (PMID 37764713, 2023). "Experimental studies suggest 25(OH)D deficiency impairs glucose-induced insulin secretion and that insulin sensitivity may improve with 25(OH)D supplementation in patients with vitamin D deficiency." (PMID 34991572, 2022). "Moreover, higher PTH and vitamin D insufficiency can be jointly associated with higher HOMA-IR: the effect of PTH on insulin release from islets depends on vitamin D-related calcium and phosphorus." (PMID 36313112, 2022). "Another study ascertained that vitamin D deficiency alters insulin synthesis and secretion." (PMID 35631273, 2022). "In addition, many studies have confirmed the close relation between vitamin D deficiency and the development of insulin dysregulation/T2DM, increased length of respiratory infections, and mortality in patients with common immunodeficiencies." (PMID 35203487, 2022).